TLR4 (toll like receptor 4)
Diseases named in the same sentence as TLR4 in open-access papers (continued):
Sharing a sentence is not in itself a finding about the gene and the disease.
adenomyosis (7 papers, 2016 to 2025). The growth of endometrial tissue inside the muscular wall of the uterine corpus. "In this study, reducing estrogen interference, we choose the patients in early proliferative phase to discuss the LPS/TLR4-induced signal pathway in eutopic and ectopic endometrium and its possible association with reproductive outcome in women with adenomyosis." (PMID 26898650, 2016). "The regulatory role of miR-17 in adenomyosis, particularly via the lncRNA H19/miR-17/TLR4 pathway, has been previously established." (PMID 41374393, 2025). "This manifests, particularly, as innate immune pathway activation: increased Toll-like receptor 4 (TLR4) expression in endometrial stromal cells in adenomyosis has been shown." (PMID 41488658, 2025). "In fibroids, H19 overexpression drives ECM accumulation via TGF-β and collagen regulation, whereas in adenomyosis, H19 acts primarily through inflammatory derepression (via miR-17 → TLR4/NF-κB)." (PMID 41226749, 2025). "Our current findings indicated that TLR4-MyD88-NF-κB had vital functions in the development of adenomyosis." (PMID 26898650, 2016). "This study suggested that stromal cells were activated by the TLR4 signalling pathway, which processed the cellular inflammatory proliferation and invasive growth involved in the pathogenesis of adenomyosis." (PMID 26898650, 2016). "This study aimed to analyse the role of the TLR4 signalling pathway on the endometrial stromal cells and reveal the mechanisms of adenomyosis, providing a theoretical basis for clinical treatment." (PMID 26898650, 2016). "Moreover, nonsteroidal anti-inflammatory drugs (NSAIDs) provide partial symptomatic relief in adenomyosis, further implicate inflammatory pathways, such as IL-18 and TLR4, in adenomyosis pathogenesis." (PMID 41209546, 2025). "We previously demonstrated that TLR4 was over-expressed in adenomyosis tissues, and the cell model indicated that stromal cells were activated by TLR4 signaling pathway, which processed the cellular inflammatory proliferation and invasive growth involved in the pathogenesis of adenomyosis." (PMID 28779087, 2017). "We found that the TLR4 signal pathway played an important role in the pathogenesis of adenomyosis." (PMID 26898650, 2016). "Our current findings may provide clues in targeting TLR4 in new therapeutic strategies for women with adenomyosis." (PMID 26898650, 2016). "The present study tested whether the LPS/TLR4 signal pathway in endometrial stromal cells is essential for the pathogenesis of adenomyosis." (PMID 26898650, 2016). "Adenomyosis demonstrates paradoxical Treg deficit with elevated Th17/Treg ratio and dominant HMGB-1/TLR4 activation (particularly in secretory phase), creating distinctly pro-inflammatory microenvironment." (PMID 41488658, 2025). "The Toll-like receptor 4 (TLR4)/MyD88/nuclear factor-kappa B (NF-κB) signaling pathway has been found to promote the secretion of various cytokines and growth factors in adenomyosis, leading to inflammatory responses and immune system alterations, thereby contributing to disease onset." (PMID 39595579, 2024). "We detected both protein and gene expression of TLR4 in eutopic and ectopic endometrial tissue derived from women with adenomyosis and endometrium without adenomyosis." (PMID 26898650, 2016). "We tested the expression of TLR4, MD2 in the endometrium without adenomyosis (CE), the eutopic endometrium with adenomyosis (EuE) and the ectopic endometrium with adenomyosis (EE)." (PMID 26898650, 2016).
allergic contact dermatitis (7 papers, 2015 to 2025). An inflammatory skin condition caused by an immune response to direct contact between the skin and an allergen. "Nickel sulphate is known to cause allergic contact dermatitis (ACD) by directly interacting with specific histidine residues in the human Toll-like receptor 4 (TLR4), which normally act as an innate immune receptor for bacterial lipopolysaccharide (LPS)." (PMID 31197444, 2019). "Previous studies have reported that Tlr4−/− mice show reduced scratching in histamine‐mediated acute itch and in chronic itch models of dry‐skin pruritus, contact dermatitis and allergic contact dermatitis." (PMID 38957035, 2024). "Several in vitro studies and mouse models of other inflammatory skin diseases have demonstrated a role for TLR4, e.g., nickel-induced allergic contact dermatitis and graft versus host disease." (PMID 26198339, 2015). "Previous in vivo experimental models of allergic contact dermatitis (ACD) to nickel have shown that epicutaneous exposure to nickel in mice, involves danger signaling via the NLRP3 inflammasome complex but was independent of Toll-like receptor 4 (TLR4)." (PMID 30653583, 2019).
Anorexia (7 papers, 2011 to 2026). Lack of desire to eat (loss of appetite). "We used activity-based anorexia (ABA) model to investigate the role of TLR4 and its contribution in anorexia-associated low-grade inflammation." (PMID 27779218, 2016). "In conclusion, we show that activity-based anorexia leads to gut inflammation from the initial period of body weight loss through TLR4 activation." (PMID 27779218, 2016). "Specifically, TLR-4 and MyD88 have been implicated in circadian responses and anorexia respectively." (PMID 21569241, 2011). "Thus, the current study assessed the sufficiency of peripheral afferents expressing toll-like receptor 4 (TLR4) to the initiation of the anorexia caused by peripheral bacterial lipopolysaccharide (LPS)." (PMID 33318075, 2021). "Finally, to investigate the effects of TLR4 deficiency in the progression of activity-based anorexia, we used wild type (WT) and TLR4−/− mice for ABA induction." (PMID 27779218, 2016). "Increased expression of Toll-like receptor 4 (TLR4) has been reported in the intestinal epithelial cells (IEC) of activity-based anorexia (ABA) mice." (PMID 41764036, 2026). "Previous data reported that lipopolysaccharides induce anorexia and a decrease of body weight through the activation of toll-like receptor 4 (TLR4)." (PMID 36079861, 2022). "The starting point of the study was to examine the involvement of TLR4 expressed by Nav1.8+ neurons in LPS stimulated rapid-onset anorexia." (PMID 33318075, 2021). "In a previous study, we observed that TLR4 membrane expression is increased during the commonly used activity-based anorexia (ABA) model in both intestinal epithelial cells (IEC) and mucosal macrophages, which was associated with increased intestinal and hypothalamic inflammatory responses." (PMID 36079861, 2022). "In summary, we demonstrated using a new mouse model that vagally-expressed TLR4 is selectively involved in stimulating the release of CGRP but not in causing anorexia." (PMID 33318075, 2021). "Contrary to our expectations, the administration of LPS did not cause rapid-onset anorexia in mice with Nav1.8-restricted TLR4." (PMID 33318075, 2021). "Early LPS-induced anorexia was investigated in control Nav1.8-Cre mice with intact Tlr4 expression." (PMID 33318075, 2021). "In mice expressing TLR4 only in Nav1.8 cells, LPS similarly failed to trigger anorexia or weight loss." (PMID 33318075, 2021). "However the potential role of TLR4-mediated response leading to low-grade inflammation during anorexia has received relatively little attention." (PMID 27779218, 2016). "Thus, the present study aimed to analyze intestinal TLR4 signaling pathway activation during activity-based anorexia (ABA), as well as the hypothalamic immune response to early weight loss." (PMID 27779218, 2016). "Contrary to expectation, our findings indicate that TLR4 signaling in peripheral afferents alone is not sufficient to initiate anorexia." (PMID 33318075, 2021). "Intraperitoneal (i.p.)administration of lipopolysaccharide (LPS), an outer cell wall component of gram-negative bacteria and Toll-like receptor 4 (TLR4) agonist, has long been known to trigger sickness behavior which includes anorexia and a decrease in locomotion, exploration and social interaction." (PMID 31338703, 2019).
aortic aneurysm (7 papers, 2014 to 2024). A ruptured aneurysm located in the wall of the proximal portion of the descending aorta proceeding from the arch of the aorta. "IL8 is mechanistically involved in the innate immune response by TLR4 signaling, induces neutrophil extracellular traps (NETs) via activation NFκB signaling, mediates hyper-signaling in aortic aneurysms, and is involved in endothelial adhesion." (PMID 36552736, 2022). "In the present study, we intended to investigate the potential effects of genetic polymorphisms in TLR4 and MMP2 individually and complex interactions in susceptibility to aortic aneurysmal diseases in a Chinese Han population." (PMID 30530865, 2019). "We also examined the interaction effect between TLR4 and MMP2 polymorphisms on the risk of aortic aneurysmal diseases." (PMID 30530865, 2019). "The objective of this study was to evaluate the interactions between TLR4 and MMP9 polymorphisms in the risk of aortic aneurysm (AA) and its subtypes." (PMID 30922233, 2019). "We aimed to evaluate the contribution of TLR4 and MMP2 polymorphisms individually and complex interactions between gene and risk factors in susceptibility to aortic aneurysm (AA) and its subtypes." (PMID 30530865, 2019). "Notably, a study investigating the effect of AOS on aortic aneurysms demonstrated that AOS could modulate the Toll-like receptor 4 (TLR4)-mediated nuclear factor-κB (NF-κB) signaling pathway, effectively inhibiting the overexpression of inflammatory factors." (PMID 38731302, 2024). "Furthermore, a recent study demonstrated in apolipoprotein E-deficient mice that it is possible to limit the inflammatory process by blocking TLR4/c-Jun N terminal kinase signaling pathway with Rosiglitazone in the initiation stages of aortic aneurysm development." (PMID 25120286, 2014). "In addition, since AA is a multifactorial disease, specific and few polymorphisms of TLR4 and MMP2 in the present study may not fully explain susceptibility to aortic aneurysmal diseases." (PMID 30530865, 2019).
carotid atherosclerosis (7 papers, 2012 to 2024). A thickening and loss of elasticity of the walls of carotid arteries that occur with formation of atherosclerotic plaques. "The Asp299Gly polymorphism in TLR4 has been associated with a lower risk of carotid atherosclerosis, and a reduction in intima media thickness in the common carotid artery, and has also been linked to decreased acute coronary events, and greater efficacy of statin therapy." (PMID 25757594, 2015). "Studies have shown that TLR4 promotes carotid atherosclerosis through increased expression of inflammatory cytokines." (PMID 37137812, 2023). "In the population-based Bruneck study, low toll-like receptor 4 (TLR4) expression was associated with a decreased risk of carotid atherosclerosis, as well as less inflammatory response to gram-negative pathogens, and high susceptibility to bacterial infections." (PMID 34198968, 2021). "Interestingly, recent immunofluorescence experiments revealed colocalization of PAR1 with toll-like receptors (TLRs)—TLR2 and TLR4—in human carotid atherosclerotic lesions, pointing to activation of TLRs and interaction with PAR1 in an innate immune response in carotid atherosclerosis." (PMID 35742805, 2022).
cerebral cavernous malformation (7 papers, 2018 to 2023). A disorder characterized by malformations in the structure of the capillaries in the brain. "Recent evidences have suggested the involvement of toll-like receptor (TLR)-4 in the pathogenesis of cerebral cavernous malformations (CCM)." (PMID 35109870, 2022). "One of the early studies in this field demonstrated certain species of bacteria increase cerebral cavernous malformation (CCM) growth in mice through activating TLR4." (PMID 35203709, 2022). "Moreover, TLR4 mediates traumatic brain injury, cerebral cavernous malformations, spinal cord ischemia-reperfusion injury, and other neurological diseases." (PMID 36523959, 2022).
cerebral malaria (7 papers, 2013 to 2022). A sequestration of Plasmodium falciparum in the brain, which can cause coma and/or seizures. "We also note that co-administration of EV-loaded miR-451a and let-7i-5p led to the significant reduction of the TLR4 dependent release CXCL10, a biomarker of cerebral malaria severity." (PMID 36618355, 2022). "However, TLR2 and 9 but not TLR4, 5, and 7 were involved in cerebral malaria (CM) infection using Plasmodium berghei ANKA (PbA)." (PMID 27511368, 2016). "Although the role of TLR2 and TLR4 in malaria remain unclear, mice deficient in TLR9 were reported to be resistant to PbA-induced experimental cerebral malaria (ECM), suggesting a pathological role of TLR9 rather than a protective role during cerebral malaria." (PMID 29495555, 2018).
cerebrovascular diseases (7 papers, 2013 to 2025). "The TLR4-mediated NF-κB pathway serves as a critical regulator of inflammatory responses, and has been extensively studied in cerebrovascular diseases and neurodegenerative diseases." (PMID 40919222, 2025). "Interestingly, TREM2 has neuroprotective effects in cerebrovascular disease by suppressing TLR4 expression and the downstream NF-κB pathway and suppressing the expression of inflammation-induced cytokines." (PMID 41208869, 2025). "It is clearly recognized in multiple brain injury pathologies that TLR4 activation plays a crucial role in the pro-inflammatory activation of leukocytes, including TBI and cerebrovascular disorders." (PMID 34372870, 2021). "No literature data exist on TLR4 role in the T2DM-associated chronic kidney and other T2DM-related cardiovascular diseases, such as carotid arterial and cerebrovascular diseases, lower limb arteriopathy, in Caucasian populations, although it is well recognised in other age-related diseases." (PMID 24803744, 2014).
chronic hepatitis B (7 papers, 2011 to 2025). "Activation of TLR4 can cause liver injury under several clinical conditions such as hemorrhagic shock, hepatic ischemia reperfusion injury, alcohol hepatitis and chronic hepatitis B." (PMID 21559380, 2011). "TLR4 was up-regulated in the hepatocytes in patients with chronic hepatitis B." (PMID 21559380, 2011). "Previous studies have shown that HMGB1 regulated Treg/IL17 ratio in patients with chronic hepatitis B, in which HMGB1 was significantly higher and induced Th17 cells but suppressed Tregs via TLR4 and IL6 pathway." (PMID 33679792, 2021). "While these data demonstrate that LPS/TLR4 interaction may not be critical to fibrosis development in chronic liver disease, activation of TLR4 as well as TLR5, TLR7, and TLR9 was actually found to be beneficial in chronic hepatitis B virus infection by reducing the viral replication." (PMID 32373617, 2020).
colorectal adenocarcinoma (7 papers, 2020 to 2025). The most common type of colorectal carcinoma. "Specifically, researchers showed that LPS caused a TLR4-dependent activation of FAK in human colorectal adenocarcinoma cells, a model of colonic epithelial cells." (PMID 35803916, 2022). "The increased expression of TLR4 is a common feature of colorectal adenocarcinoma and TLR4/MyD88 signaling has been associated with poor prognosis." (PMID 34026821, 2021). "In another study, the proinflammatory markers CD68, CD15, IL-6, and TLR4 were upregulated in colorectal adenocarcinoma compared to normal mucosa or premalignant conditions." (PMID 36649244, 2023). "TLR4 is expressed in immune cells and in various cancer cells including colorectal adenocarcinoma and mCRC." (PMID 32322173, 2020). "In regards to HM-inhibited ERK phosphorylation, TLR4 blockade reduced the inhibitory effect of HM on ERK phosphorylation detected in colorectal adenocarcinoma HT29 and mCRC SW620, as compared to HM-inhibited ERK phosphorylation detected in both cells." (PMID 32322173, 2020). "Recent studies reported that endotoxin lipopolysaccharide (LPS) induced a TLR4-dependent activation of focal adhesion kinase (FAK) in colorectal adenocarcinoma cells, suggesting that FAK may be involved in LPS-induced inflammatory responses." (PMID 35803916, 2022). "Because an increased expression of TLR4 in CRC is common and TLR4/MyD88 signaling is associated with poor prognosis, we analyzed TLR4 expression in colorectal adenocarcinoma specimen according to MMR status." (PMID 34026821, 2021). "Thus, in this present study, we verified whether TLR4 plays a key role in HM anticancer effects in colorectal adenocarcinoma and mCRC." (PMID 32322173, 2020).
cyst (7 papers, 2014 to 2023). A sac-like closed membranous structure that may be empty or contain fluid or amorphous material. "miR-214, a microRNA, restrained cyst-associated inflammation (by inhibiting TLR4) and attenuated cyst growth." (PMID 36675597, 2023). "Interestingly, TLR4 gene expression was significantly high in healthy pulp tissue compared with the periapical granuloma and cyst (P < 0.05)." (PMID 34539639, 2021). "In fact, this signalling could limit TLR4-mediated cytokine production that may occur during cyst growth, as a result of degradation of extracellular matrix." (PMID 26846700, 2016). "TLR4 profiles could be used to distinguish vocal fold disorders with similar macroscopic appearances (i.e. reinke’s edema, polyp, cyst), which are known to be difficult to clinically ascertain." (PMID 25606025, 2014).
Fever (7 papers, 2012 to 2025). Body temperature elevated above the normal range. "As a result of this experiment, we found that TLR4 and NF-κB levels were elevated in rats with yeast-induced pyrexia." (PMID 40356990, 2025). "During the process of LPS-induced fever, Toll-like receptor 4 (TLR4), the receptor for LPS, is upregulated on the cell membrane through paxillin-mediated mechanisms." (PMID 38611918, 2024). "The TLR4/NF-κB pathway is a bridge between exogenous and endogenous pyrogens in the fever progress." (PMID 40356990, 2025). "Exogenous pathogens activate the TLRs signaling pathway constituents such as TLR4, MyD88, TBK1, IRF3, and IRAK4, and subsequently stimulate the release of pro-inflammatory cytokines which promote to progress a disease by producing fever and tissue damage." (PMID 28489052, 2017).
gastric tumor (7 papers, 2013 to 2023). "TLR4 expression was evaluated by immunohistochemistry in normal gastric cardia mucosa, chronic gastric cardia inflammation, and GCC, to better understand the potential role of TLR4 in gastric cardia carcinogenesis." (PMID 29670922, 2018). "In this study, we indicate that the ASCL2 inhibition could significantly activate inflammation, weakening the development of tumor cells, and decreasing the level of biomarkers of gastric tumor through TLR4 activation." (PMID 36008864, 2022). "We analyzed TLR2, TLR4 and RAGE gene expression in human gastric tumor cells using quantitative real-time PCR." (PMID 25652880, 2015).